FZD7 (frizzled class receptor 7)
Diseases named in the same sentence as FZD7 in open-access papers (continued):
Sharing a sentence is not in itself a finding about the gene and the disease.
tumor (continued). "Interestingly, genes of Wnt signaling pathways including FZD7 and TCF7 are upregulated in tumor-adjacent stroma as compared to tumor epithelium." (PMID 36230846, 2022). "Independent of tumor characteristics (secreting or non-secreting, invasive or non-invasive), Frizzled receptor 7 (FZD7) was downregulated in PitNETs." (PMID 35203352, 2022). "The Western blot and real-time PCR findings exhibited that the combination therapy reduced the expressions of Fzd7, Nedd9, VEGF-α, Vim and Mmp9 and upregulated E-Cad in 4T1 cells and liver and tumor tissues, thus preventing Wnt/β-catenin signaling and averting metastasis in TNBC." (PMID 36079579, 2022). "As a pair of negative control genes, we selected the Wnt1, a ligand, and Fzd7, a co-receptor in Wnt signaling, and overexpressed them in tumor cells." (PMID 34373756, 2021). "A series of studies in vitro and in vivo indicated that SHH002-hu1 could effectively target Fzd7+ cells and Fzd7+ TNBC tumor tissue, and inhibit TNBC via blocking Wnt/β-catenin signaling pathway." (PMID 33436039, 2021). "The expression of AT1R, ACE, AGT, glutamine synthetase, CD44 and Fzd7 were not significantly changed in the tumor tissues from the captopril treated mice compared to control mice (respectively)." (PMID 34073112, 2021). "Reduced FZD7 levels led to a decrease in tumour growth when 50,000 and 5,000 cells were injected, while no changes were observed with a saturating concentration of 500,000 cells." (PMID 33082334, 2020). "While the expression of MIST and FZD7 at the tumor surface, tumor center, and invasion front was interrelated significantly, no such interrelation between different tumor compartments was found for LGR5." (PMID 31827644, 2019). "Results showed that expression of FZD7 was significantly higher in tumor tissue than that in the adjacent non-tumor tissues." (PMID 27852064, 2016). "Nevertheless, our findings do not differentiate the function of FZD7 on tumor initiation from its function on cell proliferation in the bulk of metastases during metastatic growth." (PMID 26808375, 2016). "Interestingly, knockdown of miRNA-126 repressed the expression of tumour suppressor genes ERRFI1 and SPRED1, but increased Wnt pathway activation via increased FZD7 expression." (PMID 27196929, 2016). "To validate the DASL observations, we performed quantitative RT-PCR on the representative upregulated genes, and observed that the expression of mRNAs, including MMP7, NOTCH1, FZD7, were significantly higher in TN tumor samples than in non-TN tumor samples." (PMID 24143235, 2013). "Interestingly, the CpG sites with strongest ability to discriminate tumor from surrounding tissue were found in the promoter of genes hypermethylated in HCC samples (e.g. APC, RASSF1A, CDKN2A, and FZD7)." (PMID 20305825, 2010). "FZD7 mRNA levels were significantly higher in stage II, III or IV tumours than in non-tumour tissues (P<0.005), and overall survival was shorter in those patients with higher FZD7 expression (P<0.001)." (PMID 19773752, 2009). "Complementary studies in 3D tumor organoids confirm these findings: Organoids derived from MMTV-Wnt1 tumors preserve the cellular heterogeneity and lineage architecture of the in vivo tumors, with luminal and basal compartments clearly demarcated and Fzd7 expression restricted to basal cells." (PMID 41218118, 2025). "This study observed that silencing HOTAIR preventes tumor growth in a xenograft model, while the silencing of miR-129-5p reversed HOTAIR gene silencing effects and FZD7 reinstated the inhibitory effect of miR-129-5p, suggesting that HOTAIR regulates the miR-129-5p/FZD7 axis." (PMID 36997931, 2023). "Notably, the tumor growth of Fzd7‐rescued Fzd5‐KO Patu8988s did not alter by cholesterol modulation." (PMID 35975457, 2022). "FZD7 expression is significantly higher in TNBC than in non-TNBC tumor tissues." (PMID 33805447, 2021).
tumor (continued). "Both FZD7 and c-MYC are considered to be potential markers of tumor cells; therefore, we speculated that the link between proliferation and apoptosis in the immature Sertoli cells was similar to that in tumor cells, and that this mechanism was influenced by the expression level of FZD7." (PMID 37047150, 2023). "F7L6 did not rescue the growth of tumor organoids derived from WT (non-HF7) MMTV-Wnt1 tumors, confirming selectivity of F7L6 for human FZD7 and hFzd7, but not WT Fzd7." (PMID 41218118, 2025). "Frizzled family receptor 7 (FZD7), which mediates both classical and non-classical Wnt signaling, plays an important role in maintaining SC properties as well as tumor development." (PMID 39513610, 2024). "We also tested the luminal tumor MMTV-PyMT model in xenograft models in vivo, which do not overexpress Fzd7 and its organoids are resistant to TcdBFBD in vitro." (PMID 37943878, 2023). "FZD7, a member of the FZD family, regulates tumor metastasis through modulating canonical and non-canonical Wnt pathway." (PMID 33663510, 2021). "The mRNA levels for several critical components of the pathway (BIRC5, CD44, FZD7, c-MET, MMP7, c-MYC, NOTCH1, PPARD, and VEGF) were significantly increased (DASL signal intensity) in TN tumor samples as compared to non-TN tumor samples." (PMID 24143235, 2013).
cancer (81 papers, 2009 to 2025). A tumor composed of atypical neoplastic, often pleomorphic cells that invade other tissues. "Of theten family members, FZD7 is upregulated in multipleforms of cancer and is associated with cancer cell proliferation andtumor development." (PMID 39670643, 2024). "Up-regulation of Fzd7 is implicated in several human cancers caused by activation of Wnt pathways accompanied by an increase in cell proliferation, invasion, metastasis, and recurrence." (PMID 35655594, 2022). "The Wnt signaling receptor Frizzled family receptor 7 (FZD7) is linked to the maintenance of stem cell features as well as cancer progression." (PMID 36276155, 2022). "To investigate the association of Fzd7 with BC cell mesenchymal phenotype, we first interrogated Cancer Cell Line Encyclopedia (CCLE) database and GSE12777 database." (PMID 32894152, 2020). "To validate these results, we performed flow cytometry analysis of known surface molecules implicated in cancer progression including frizzled 7 (FZD7), CD44, MUC-1, and integrins α2, β4, αvβ3, β3, and α4." (PMID 32352029, 2020). "The FZD7 gene encodes Frizzled-7, a member of the Frizzled family, is a receptor of Wnt signaling, and has been reported to be an oncogene in various cancers." (PMID 31399111, 2019). "Frizzled family receptor 7 (FZD7), a Wnt signaling receptor, is associated with the maintenance of stem cell properties and cancer progression." (PMID 30548372, 2019). "Experimental overexpression of miR199a in human HepG2 HCC cells was able to repress cancer growth in vitro and in vivo, and was associated with inhibition of FZD7." (PMID 27196929, 2016). "The immunoprecipitation assay indicated that FZD7, which is universally upregulated in cancer, could associate with TBC1D1." (PMID 36371204, 2022). "Overexpression of FZD7 is associated with EMT in many types of cancer." (PMID 34604862, 2021). "FZD7, which serves as a Wnt receptor in the body, is required for both Wnt signaling and the development of cancer." (PMID 40171220, 2025). "The findings showed that when cancer cells were treated with pistachio hull essential oil, the β-catenin protein and frizzled class receptor 7 (FZD7) were suppressed." (PMID 40699792, 2025). "Multiple FZD receptors show increased expression in cancer lines, and some FZDs, such as FZD7, show a decrease in mRNA and protein expression in response to sirtuin inhibitors." (PMID 40376615, 2025). "FZD7/β-catenin/TP63 Axis: Specifically activated in cancer cells, conferring resistance to ferroptosis by regulating genes involved in glutathione (GSH) metabolism." (PMID 41479924, 2025). "Mechanistically, we found that cytoplasmic KIAA1429 promotes WNT pathway activation by binding and stabilizing FZD7, thereby further enhancing cancer stemness and oxaliplatin resistance." (PMID 40611274, 2025). "Further analysis of single-cell sequencing data (GSE103322) revealed higher enrichment of FZD7 in cancer cells compared to FZD5." (PMID 38246919, 2024). "FZD7 is considered a possible mediator between canonical and non-canonical Wnt signaling pathway regulation in hLESCs, as shown in cancers." (PMID 37509479, 2023). "Immunohistochemical assay showed that 31/42 cancer tissue samples (73.81%) were positive for FZD7 and 8/42 paracancerous tissues samples (16.67%) were positive for FZD7, with mean IHC scores of 8.2 ± 3.5 and 2.7 ± 3.2, respectively (P < 0.05)." (PMID 35854234, 2022). "Although some research has shown that FZD7 shRNA can reduce TNBC cell proliferation, viral therapy can cause unfavorable immunological responses, and adenovirus-mediated cancer gene therapy is still being investigated." (PMID 36276155, 2022). "The Fzd7 expression in cancer tissues was significantly higher compared with the paracancerous tissues." (PMID 33934523, 2021). "Frizzled-7 (FZD7) has been identified as an oncogene that is responsible for cancer cell growth; the activation signaled by Wnt." (PMID 32276343, 2020).
cancer (continued). "FZD7, widely known as the most common reporter of Wnt, has been recognized as a target for cancer therapy, as it can play an important role in controlling endothelial cell proliferation by inhibiting the Wnt–β-catenin signaling regulators." (PMID 31419987, 2019). "Frizzled-7 (FZD7) is up-regulated in LUSC, and it is a protein associated with the WNT signaling pathway - a usual suspect in cancer." (PMID 31429720, 2019). "Further support for a fundamental role of miR-710 in cancer derives from the fact that its predicted targets include ADAM10, PDGFRA, and FZD7, which are linked to senescence and stemness." (PMID 31834924, 2019). "In this study, we use OC as the model system to explore how the FZD7 pathway contributes to the aggressiveness of cancer cells." (PMID 30548372, 2019). "FZD7 is upregulated in multiple solid cancers and is involved in cancer development and progression." (PMID 31419987, 2019). "To date, several miRNAs, such as miR-485-5p, miR-488, miR-144-3p, and miR-27b inhibit cancer progression by targeting FZD7." (PMID 31419987, 2019). "It has been strongly confirmed that FZD7 is highly expressed in multiple cancers, including HCC14–16." (PMID 30154476, 2018). "FZD7 is a member of the Frizzled receptor family and has been shown to be important in cancer development and progression by activating Wnt pathways." (PMID 29416676, 2018). "And overexpressed FZD7 promotes the progression of cancers by inducing the activation of Wnt signaling pathway." (PMID 30154476, 2018). "Fzd7 is frequently up-regulated in a variety of cancers including colon cancer, breast cancer, hepatocellular carcinoma, lymphoblastic leukemia, Wilm’s tumors, glioblastoma, ovarian cancer melanoma, chronic myeloid leukemia and gastric cancer." (PMID 29207657, 2017). "Of the 10 members of the Fzd family, Fzd7 is the most important member involved in cancer development and progression." (PMID 29207657, 2017). "Of the 10 members of the Fzd family, Fzd7 is the most important member regulating cancer development and progression." (PMID 29207657, 2017). "FZD7 expression is also increased in a side population of cells isolated from GC cell lines, which were found to have increased cancer stem cell properties, supporting a role for FZD7 in promoting GC." (PMID 27196929, 2016). "It has been recently reported that FZD7 is upregulated in several human cancers, and also appears to promote tumorigenesis and cancer progression." (PMID 27852064, 2016). "In cancer, the function of FZD7 has mostly been attributed to canonical WNT signaling, although some evidence on non-canonical signaling has been presented." (PMID 26808375, 2016). "Inhibition of FZD7 using a blocking antibody resulted in reduced clonality of cancer cells isolated from human WT samples, and apoptosis in those cells which expressed FZD7." (PMID 27196929, 2016). "FZD7 has been demonstrated as a critical receptor of the Wnt signaling and involves in tumorigenesis and metastasis in many cancer types." (PMID 26716419, 2016). "FZD7 has been shown to play essential functions in stem cell maintenance from multiple tissues and cancer types and WNT signaling is well known to regulate stem cell properties." (PMID 26808375, 2016). "Collectively, these studies reveal some of the factors regulating Fzd7 expression, and illustrate its importance in several biological contexts, from development and regeneration through to homeostasis and cancer." (PMID 27196929, 2016). "The WNT signaling is implicated extensively in stem cell maintenance and differentiation, and FZD7 has been shown to regulate stem cell functions in a variety of normal tissues and cancer types." (PMID 26808375, 2016). "Recent works suggested that FZD7 emerges as a crucial regulator for stemness features in both human embryonic stem cells and cancer stem cells." (PMID 27105493, 2016).
cancer (continued). "It has been demonstrated that siRNA (small interfering RNA) knockdown of FZD7 displayed anti-cancer activity in vitro and in vivo due to the inhibition of the canonical Wnt signaling pathway." (PMID 26056595, 2014). "Understanding the mechanisms regulating FZD7 expression in highly invasive cancers is important to the development of more efficacious treatments." (PMID 24897117, 2014). "The results from our study agree with published research in that FZD7 has an important role in cancer cell growth and development, and we have shown that SIRT1 can regulate the expression of this critical receptor at the transcriptional level." (PMID 24897117, 2014). "Though beyond the scope of this study, it would be of interest to examine the relationship between FZD7, Dvl, and heterotrimeric G-proteins and investigate their combined contribution to the development and maintenance of cancer cells." (PMID 24897117, 2014). "Perhaps by combining current frontline therapies, with inhibitors of SIRT1 or SIRT2, along with a FZD7 antagonist, we can create a synergistic effect in cancers with an over-active Wnt pathway." (PMID 24897117, 2014). "Several research groups have attenuated the action of over-expressed Fzd7 in cancer cells using different methods such as an anti-FZD7 antibody, an extracellular peptide of FZD7 (soluble FZD7 peptide), small interfering peptides or a small molecule inhibitor." (PMID 25313882, 2014). "Furthermore, we found that cytoplasmic KIAA1429 promotes WNT pathway activation by binding and stabilizing FZD7, thereby further enhancing cancer stemness and oxaliplatin resistance." (PMID 40611274, 2025). "Furthermore, we examined a key developmental pathway linked to cancer stemness in OC spheroids, the Wnt pathway, and ILK inhibition markedly downregulated several pathway members, including Fzd7 and β-catenin target gene c-Myc at mRNA levels." (PMID 38822429, 2024). "Therefore, it is attractiveto develop therapeutics targeting FZD7 for cancer treatment.Structure-based virtual screening has identified compound 28, whichinhibited WNT/β-catenin signaling based on the luciferase-basedreporter gene TOPFlash assay." (PMID 39670643, 2024). "Some studies showed that FZD7 appears to promote tumorigenesis and cancer progression." (PMID 37091799, 2023). "In addition to vantictumab, an oligopeptide Fz7-21 and a small molecule SRI37892 have been evaluated as a new Fzd7-targeting agent to disrupt the Wnt signaling pathway for inhibiting intestinal stem cell function and cancer progression." (PMID 36339397, 2022). "For this reason, targeting Fzd7 CRD may be an effective therapeutic approach for cancers with overactive Wnt signaling pathways." (PMID 35655594, 2022). "Among the ten FZDs, FZD7 is the most studied member in cancer." (PMID 36620565, 2022). "In addition, it has been demonstrated that siRNA knockdown of FZD7, the anti-FZD7 antibody displayed anti-cancer activity in vitro and in vivo mainly due to the inhibition of the canonical Wnt signaling pathway." (PMID 36276155, 2022). "Therefore, targeted inhibition of FZD7 represents a rational and promising new approach to cancer therapy." (PMID 36276155, 2022). "FZD7 is the most important WNT receptor involved in cancer development and progression in mammals." (PMID 34765604, 2021). "FZD7 played important roles in various human cancers containing CRC." (PMID 33663510, 2021). "The immunohistochemical assay showed that 28 cases (75.7%) were positive for Fzd7 among the 37 cancer tissue samples and seven cases (18.9%) were positive for Fzd7 in the 37 paracancerous tissues, and the IHC scores were 6.2 ± 3.4 and 2.9 ± 3.1, respectively (p < 0.05)." (PMID 33934523, 2021). "Increased expression of Fzd7 leads to increased tumorigenesis in both cancer types." (PMID 34671643, 2021). "For instance, compounds that bind to the transmembrane domain of Fzd7 and interfere with Wnt binding could reduce oncogenic signaling in many cancer types." (PMID 34671643, 2021).